SDHB (succinate dehydrogenase complex iron sulfur subunit B)
Diseases named in the same sentence as SDHB in open-access papers (continued):
Sharing a sentence is not in itself a finding about the gene and the disease.
tumor (continued). "The difference between SDHB and RET-PCPG became even more evident when the tumor cells of each patient were compared to chromaffin developmental cell types." (PMID 36046044, 2022). "The immunohistochemical (IHC) result showed tumor cells were CD117(+), DOG-1(+), SDHB(-), and Ki-67 5%." (PMID 36387130, 2022). "A further 378 TS-Hyper probes within CpG islands were shared between SDHB-RCC and one other tumor type." (PMID 36455002, 2022). "For both HLRCC and SDHB-RCC the number of primary tumors was relatively small, limiting the extent of this analysis, but there is an obvious difference between the tumor types." (PMID 36455002, 2022). "We aimed to determine the transcriptional programs that are active across tumor cells and then identify the programs that are differentially enriched between RET and SDHB tumors." (PMID 36046044, 2022). "This is consistent with our study, since in 62% (6/8) of the patients with this large deletion in the SDHB gene, the initial finding was a PGL tumor." (PMID 36685941, 2022). "Accordingly, we observed up-regulation of the Succinate dehydrogenase complex, a tetramer consisting of SDHA, SDHB, SDHC and SDHD subunits that exerts a critical tumor suppressive role and has been proposed as an important therapeutic target in HCC." (PMID 36203462, 2022). "The transcription programs related to ion channel activity (transmembrane transport) separated the SDHB and RET tumor cells." (PMID 36046044, 2022). "We present evidences that GIPC2 upregulates p27 and suppresses PPGL cell proliferation and tumor growth both in vitro and in vivo, and we propose a GIPC2-based mechanism through which sporadic and RET- and SDHB-related hereditary PPGLs develop." (PMID 33947839, 2021). "To further establish the relationship between miR-483-3p and SDHB expression, we compared miR-483-3p and SDHB protein expression in GIST tumor samples." (PMID 34638938, 2021). "The management of patients found to have SDHB gene mutations must be tailored to the individual since presentation can be varied: age of presentation, location of the primary tumor, metastases at diagnosis, benign PGLs, and identification of concomitant non-PGL tumors." (PMID 33564614, 2021). "Immunohistochemically, the tumor cells were diffuse and strongly positive (+++) or moderately positive (++) for CD10, P504S, vimentin, PAX8, RCC, AE1/AE3, and SDHB." (PMID 31828108, 2019). "Thus, loss of SDHB expression may promote tumor development and progression not only via the loss of growth control but also by conferring tumor initiating and dissemination abilities." (PMID 31877753, 2019). "Tumor sections from the GIST case and a panel of ~75 additional GISTs were subjected to immunohistochemistry (IHC) for the SDHB subunit." (PMID 28768491, 2017). "Archival tumor samples were available for four patients from group A (RCC samples from probands 2,3, 11, and 12 and a PC from proband 2) and histology review and SDHB immunostaining was performed." (PMID 28973655, 2017). "mTOR phosphorylation was detected in all the three SDHB-related PPGLs, while it was detected only in one VHL-related tumor." (PMID 27990160, 2016). "While elucidating other possible differences between SDHB-related PHEO and PGL, we demonstrated that the size of the primary tumor for patients with PHEOs seems to be less important for patient survival than for PGL." (PMID 25048685, 2014). "Analysis of SNP array data showed loss of heterozygosity (LOH) located to the genomic coordinates of the respective gene in 1/1 SDHB, 11/11 VHL and 3/3 NF1-related tumours." (PMID 24466223, 2014). "We chose this approach to avoid identifying differentially expressed proteins in direct comparisons of SDHB and VHL-PHEOs/PGLs that may be due to tumor location, the different mutations, or other factors that are not necessarily related to the aggressive behavior of SDHB tumors." (PMID 22859959, 2012).
tumor (continued). "Nevertheless, their tumor aggressiveness is distinct: PHEOs/PGLs metastasize rarely in VHL-, but frequently in SDHB-patients." (PMID 22859959, 2012). "Additional experiments on LDH enzyme activity or measurement of tumor lactate levels in fresh tumor tissue from SDHB- and VHL-PHEOs/PGLs will be of great interest for judging the functional impact of elevated LDHA levels in SDHB-PHEOs/PGLs." (PMID 22859959, 2012). "Immunohistochemical staining showed tumor cells positive for SYN, CgA, CD56, S-100 and SDHB, with no SDHB loss." (PMID 40589642, 2025). "The overall median follow-up period of the subjects without a tumor was 5.54 years (1.08–17.7); 4.09 years (3.00–5.17) for SDHA, 5.92 years (2.33–13.33) for SDHB, and 4.83 years (1.08–17.17) for SDHD variant carriers." (PMID 39881751, 2025). "FDG uptake correlates with tumor aggressiveness, reaching lesion-based sensitivities of ~83% in SDHB-positive tumors, while being lower in SDHB-negative cases." (PMID 41268153, 2025). "Higher stage tumors, (C2, C3 with consistent intradural tumor growth) especially if with SDHB genetics, cannot be resected without sacrifice of the nerves." (PMID 41440503, 2025). "Additionally, in this case, tumor cells don’t express CD117, TFE3, HMB45, or SDHB, but express FH and INI1(SMARCB1)." (PMID 41306531, 2025). "Similarly, the levels of SDHB and UQCRC2, as examined by immunohistochemistry, were also increased in HCT15-AA tumor grafts compared with HCT15 tumor." (PMID 39856069, 2025). "These tumours are positive for CK7, CD117, Cathepsin K, and SDHB." (PMID 38265103, 2024). "Immunohistochemical studies on both tumours showed KIT and DOG-1 positivity, with SDHB retained." (PMID 37663588, 2023). "Silencing of SDHB was shown to promote overexpression of HIF-1α, a tumor-promoting factor." (PMID 37110218, 2023). "SDHA staining was retained whilst SDHB expression was reportedly heterogeneous from intensely positive immunostaining in some tumour cells to absent protein expression in others; no LOH was identified." (PMID 35938916, 2022). "Tumour tissue showed no SDHB and SDHA expression alongside LOH, suggesting the SDHA variant was contributory." (PMID 35938916, 2022). "At least two tumours (Tu23, Tu53) were not linked to SDH variants, as determined by sequencing of the SDH genes or retained expression of SDHB upon SDHB immunohistochemical staining." (PMID 36178902, 2022). "Moreover, the result of Western blots showed that the expressions of SDHB and CCS were downregulated and that of ULK1, CDKN2A, and CMC1 were upregulated in tumor tissues compared with normal tissues." (PMID 36505872, 2022). "Tumour cells lacked SDHB staining at IHC but expressed SDHA; preserved SDHA IHC being a recognised phenomenon in SDHB, SDHC and SDHD pathogenic variants." (PMID 35938916, 2022). "We retrospectively reviewed the patient’s daughter’s renal tumor, which consisted of eosinophils and oncocytes with multiple cytoplasmic vacuoles; immunohistochemical staining of SDHB in the tumor lesion was negative." (PMID 35869040, 2022). "The results from HPA database showed that the immunohistochemical staining intensity of SDHB, GZMA, BTK, EEF2K, and NR1H2 in glandular cells of normal tissues was stronger than tumor cells, demonstrating that these genes were significantly expressed in normal colon tissues than in tumor tissues." (PMID 35912258, 2022). "Targeting NRF2-dependent GSH synthesis was effective in the metastatic model of SDHB-silenced PHEO/PGL, thus, more strategies to prevent the overall production and/or availability of GSH in tumor cells may be beneficial in future PHEO/PGL therapies." (PMID 34359671, 2021).
tumor (continued). "123I-MIBG and 111In-pentetreotide scintigraphy should not be used as first-line imaging studies for initial tumour screening in asymptomatic SDHA, SDHB, SDHC or SDHD-pi mutation carriers (Grade A)." (PMID 34021277, 2021). "Conversely, negative immunohistochemistry for SDHB and SDHA is only seen in tumours with SDHA mutations." (PMID 34834591, 2021). "The fourth edition of the World Health Organization’s (WHO) classification of endocrine tumours mentioned negative IHC for SDHB as an important marker for this group of tumours." (PMID 34356532, 2021). "Indeed, in SDHB-silenced PHEO models (MTT cells), PARP inhibition with olaparib in combination with a chemotherapeutic agent effectively reduced tumor proliferation, metastasis, and aggressive phenotypes in vivo." (PMID 34359671, 2021). "IHC for SDHB showed normal protein expression, and genetic analysis of the tumor tissue revealed the absence of SDHB LOH." (PMID 33113876, 2020). "Negative or weak diffuse SDHB staining was found in nine out of ten cases with pathogenic/likely pathogenic SDHD variants; one SDHD-mutated tumor showed positive staining of all SDH subunits." (PMID 32971818, 2020). "Whereas overall SDHB and IDH2 were moderately correlated in the tumor (Spearman, ρ = 0.37, adj." (PMID 32323921, 2020). "To evaluate whether the Ala45Thr variant was associated with changes in expression of these proteins, we used immunohistochemistry (IHC) to assess SDHA and SDHB protein levels in normal renal and RCC tumor tissue from the female proband." (PMID 30680959, 2019). "PCC1 and PCC6 showed heterogeneous labeling for SDHB, with foci of tumor cells that were immunohistochemically negative for SDHB and areas that were weakly positive." (PMID 31052272, 2019). "No areas of negative staining in tumor cells were identified throughout the different sections on SDHB immunohistochemistry." (PMID 31092265, 2019). "Mutations in the succinate dehydrogenase (SDH) subunits (mainly SDHB and SDHD) lead to familial paraganglioma syndromes, and it has been noted that some of these tumours resemble the hypoxia-induced carotid body enlargement observed in individuals living at high altitudes." (PMID 29772792, 2018). "The tumor cells were negative for SDHB, CD117, CK7, CK20, CD10, vimentin, RCC, S100, HMB-45, Melan-A, myogenin, SMA, calretinin, inhibin, DOG1, E-cadherin, and CD56." (PMID 30482207, 2018). "Western blot analysis was also used to measure SDHB protein levels in primary HCC tumor tissues and the surrounding non-cancerous tissues." (PMID 29449614, 2018). "In a large multicenter study, 62 of 69 PPGLs associated with mutations in SDHB/C/D/AF2 were negative for SDHB immunohistochemistry, whereas two SDHD-mutated tumours were scored as immunopositive." (PMID 26273102, 2015). "Loss of chromosomal arm 1p encompassing the SDHB locus, as well as losses of 11p—mostly present in SDHD tumours—and 17p were also frequent, yet not exclusive of SDHx tumours." (PMID 25625332, 2015). "Whole-exome sequencing data for all eight tumours with editing level >2.25% showed complete absence of any sequence variation at c.136 at the genomic level (depth of coverage for SDHB c.136 ranging from 40 to 111, with mean=77)." (PMID 25898173, 2015). "Analysis failed due to corrupted data in two cases, one SDHB and one NF1-related tumour." (PMID 24466223, 2014). "No tumor formation or any abnormalities were detected in SdhB+/− animals as monitored by abdominal palpation and weight measurement." (PMID 25126540, 2014). "SDHB staining is absent in the tumor tissue of all three WT GISTs, while the mutant GIST and normal cell compartments within the WT sections stain positive." (PMID 23730622, 2013). "Thus, we evaluated levels of malondialdehyde as an index of lipid peroxidation, and dihydroethidium (DHE) fluorescence for SDHB- and VHL-derived tumor tissues." (PMID 22859959, 2012).
tumor (continued). "Thus, while both tumor types show an increased ratio of LDHA to B, SDHB-derived tumors show a significantly increased overall expression of LDH." (PMID 22859959, 2012). "Importantly, the expression of SDHB is lost in all SDH-deficient neoplasms irrespective of the specific SDH subunit (SDHA, SDHB, SDHC, and SDHD) affected by a genetic mutation." (PMID 37999735, 2024). "SDHB mutation causes nonfunctional PGL and high malignant potential of tumor." (PMID 36945070, 2023). "Interestingly, metformin lowers the migratory capacity specifically in SDHB-silenced cells cocultured with fibroblasts but not in wildtype tumor cells." (PMID 36897220, 2023). "Tumor cells contrast with neighboring (non-tumoral) SDHB positive cells." (PMID 36835457, 2023). "Thus, the downregulation of SDHB expression in human HCC leads to a metabolic shift from aerobic respiration to glycolysis and the induction of the Warburg effect, ultimately facilitating tumor malignancy." (PMID 37808079, 2023). "In contrast, tumor cells are negative for both SDHA and SDHB in SDHA-deficient RCC1." (PMID 35869040, 2022). "These are Patient 8 diagnosed at age 13 years with non-metastatic secreting-PGL tumor of lumbosacral location in whom the recurrent CNV in SDHB was identified, and Patient 10 diagnosed at age 9 years with non-metastatic secreting-PCC tumor, who carries the pathogenic variant in the VHL gene." (PMID 36685941, 2022). "Moreover, one tumor (143tc) showed intratumoral immunohistochemistry heterogeneity and was characterized by both positive and negative SDHB staining." (PMID 36614070, 2022). "Identifying pathogenic SDHB variants in patients with PPGL is essential to the management of patients and relatives due to the increased risk of recurrences, metastases and the emergence of non-PPGL tumours." (PMID 34452955, 2022). "Therefore, SDHB-absent tumor immunostaining suggests the presence of an inactivating germline SDHA, SDHB, SDHC, or SDHD followed by a somatic loss in the second allele of the gene." (PMID 36091175, 2022). "If SDHB staining in the tumor cells is evidently less intense compared to non-tumoral cells, or if it shows a weak diffuse cytoplasmic blush instead of a granular staining pattern, SDHB immunohistochemistry should be regarded negative." (PMID 34181326, 2021). "SDHB immunostaining might appear falsely negative in tumor areas with clear cytoplasm, for example in clear cell RCC." (PMID 34181326, 2021). "In addition, the absence of SDHB immunostaining in tumor cells, probably caused by altered assembly or SDH complex stability, is a reliable identifier of PPGLs caused not only by SDHB mutations, but also by any other SDHx mutation." (PMID 31100940, 2019). "However, SDHB IHC was not performed, and there was no SDHD genetic analysis described for the GIST, so it is difficult to say if the tumor was SDH-deficient." (PMID 28768491, 2017). "However, data on the prevalence of SDHB in INETs and its implications on tumor differentiation and prognosis are still lacking, to the best of our knowledge." (PMID 24213468, 2012). "However, for PHEOs/PGLs pseudo-hypoxia is not an indicator of tumor aggressiveness: SDHB- and VHL-derived PHEOs/PGLs share a pseudo-hypoxic phenotype, while exhibiting quite distinct risks for the development of metastases." (PMID 22859959, 2012). "This patient showed a large deletion affecting SDHB, but as no tumor material was available, the relation of SDHB to the GIST could not be demonstrated." (PMID 19368708, 2009). "This suggests that the degree of tumor stemness of PPGLs affects the patient metastasis and progression, and it may predict the metastasis probability in patients without SDHB and cancer progression through changes in its stemness characteristics in the future." (PMID 40150683, 2025). "SDHB mutations were evaluated but it could not be confirmed as a major prognostic parameter in PPGL and suggest additional key molecular events involved in tumour progression." (PMID 37113718, 2023).
tumor (continued). "Culturing pheochromocytomas from animal tumours led to the development of the rat PC12 cell line, which carries a Max gene variant, and the MPC and derived MTT mouse cell lines that originated from the Nf1 knockout mouse, as well as the more recent RS0 cell line from rats lacking SDHB." (PMID 36178902, 2022). "We later performed comprehensive genomic profiling on the tumor samples, including PGL and GIST from patient 1 and PGL from patient 2, and searched for novel actionable mutations, including in all succinate dehydrogenase subunits, as the IHC results were negative for SDHB." (PMID 33031286, 2020). "Furthermore, interpretation of SDHB IHC in tumor areas with clear cytoplasm is not recommended because staining might appear negative." (PMID 31362359, 2019). "Its functions in the metabolic rewiring of tumor cells are poorly understood, but it might be involved in glutamine metabolism as it inhibits GLS and in OXPHOS and TCA regulation, as it decreases SDH activity by targeting both SDHA and SDHB and it inhibits PDC." (PMID 30197878, 2018). "However, as observed in single SdhB+/− mice, a tumor phenotype was not displayed by this double KO." (PMID 25126540, 2014). "Some patients with SDHB-related PPGL tumors have an excess level of catecholamine secretion; however, the exact role of this excess secretion in tumor progression is not entirely known." (PMID 41155475, 2025). "The tumor was histologically composed of oncocytic cells that expressed KRT7, vimentin, SDHA, SDHB and fumarate hydratase, but not KIT, GATA3 and alpha-methylacyl-CoA racemase." (PMID 39980061, 2025). "CIMP-specific probes were selected that had β-values >0.5 in all 21 HLRCC/SDHB-RCC tumors and <0.2 in all 24 non-CIMP tumor and normal samples." (PMID 36455002, 2022). "NRF2(E79Q) rescued tumour growth and the expression of NHE1 and SDHB—but not p65 or p62—in DDR1KD cells, regardless of Col I status." (PMID 36198801, 2022). "Accordingly, ablation of DDR1 inhibited tumour growth, p65, p62, NRF2, NHE1 and SDHB expression in Col IWT pancreata but did not reduce it further in Col Ir/r pancreata." (PMID 36198801, 2022). "Immunohistochemically, the tumor cells were positive for Vim, CD117, PDGFR, while negative for SDHB." (PMID 33612108, 2021). "Immunohistochemically, the tumor cells are positive for CK7, CAIX, and PAX8, with absence of staining for CD117 and SDHB." (PMID 34680979, 2021). "The tumor tissues were immunohistochemically examined by using the EnVision detection kit and was found to be negative for MGMT and positive for SDHB, with a Ki-67 index of 1%." (PMID 32132978, 2020). "Immunohistochemically, the tumor cells were diffuse moderately or strongly positive for CD10, P504S, vimentin, PAX8, RCC, AE1/AE3, and SDHB and focally positive for CK7 and CA IX while negative for cathepsin K, HMB45, Melan-A, Ksp-cadherin, and CD117." (PMID 31828108, 2019). "Although tumor cells show increased OXPHOS-related enzymes (SDHA, SDHB, ATP-synthase) no apoptotic activity (AI < 10%) in cancer cells was observed in those highly metabolic active regions." (PMID 25048361, 2014). "Since VHL-PHEOs/PGLs have a better prognosis than SDHB-PHEOs/PGLs, the difference in HK2 does not seem to contribute to their distinct tumor aggressiveness in these particular tumors." (PMID 22859959, 2012). "Unlike in the cell model, in human tumor tissue no change in expression of the mainly cytosolic SOD1 (P00441) was observed when comparing VHL- and SDHB-derived PHEOs/PGLs." (PMID 22859959, 2012). "Additionally, in this case, the tumor cells showed Ki67<5%, and did not express CD117, TFE3, HMB45, or SDHB, while expressing FH and INI1(SMARCB1)." (PMID 41306531, 2025). "Importantly, we confirm SDHB-mutant PCPG are molecularly distinguishable from other PCPG genotypes, while parasympathetic (non-chromaffin) tumours including HN-PG had a very distinct molecular profile." (PMID 38978571, 2024).